CD4 (CD4 molecule)
Diseases named in the same sentence as CD4 in open-access papers (continued):
Sharing a sentence is not in itself a finding about the gene and the disease.
tuberculosis (continued). "The predicted probability of M tuberculosis BSI in hospital inpatients with HIV-associated tuberculosis, WHO danger signs, and a CD4 count of 76 cells per μL (the median for the cohort) was 45% (95% CI 38–52)." (PMID 32178764, 2020). "Traditionally, it is thought that protective immunity to tuberculosis (TB) is primarily mediated by T cells, with CD4+ T cells playing a central role." (PMID 32793233, 2020). "We excluded 15 067 study participants (229 tuberculosis events) because of insufficient follow-up time (n = 1490), missing CD4+ T-cell data (n = 2060) or both (n = 11 517), leaving 58 776 in the analyses with 704 tuberculosis events." (PMID 32501837, 2020). "M72/AS01E has induced potent M72-specific humoral and polyfunctional CD4+ T-cell mediated immune responses in adults treated for tuberculosis." (PMID 33133057, 2020). "In Mycobacterium tuberculosis infection, naïve T cells that encounter mycobacterial antigens through dendritic cells (DCs) induce various CD4+ T-cell responses; therefore, appropriate DC activation is the key for protective immunity against tuberculosis." (PMID 33105734, 2020). "S1, was independently associated with risk of HIV-SN in the final model along with greater weight, tuberculosis and nadir CD4 T-cells/μL (p = 0.0003, Pseudo R2 = 0.22)." (PMID 31936167, 2020). "In patients with active TB, blood CD4+ T-cell counts are generally diminished and slowly increase with anti-tuberculosis treatment." (PMID 32033104, 2020). "We here report four cases of patients aged 28, 36, 42 and 52 years co-infected with HIV and tuberculosis (multifocal tuberculosis in 2 patients, miliary tuberculosis, bacteriologically confirmed tuberculosis), all with CD4 < 100 cells/mm3." (PMID 33425174, 2020). "The reconstitution of Mycobacterium tuberculosis antigen-specific CD4 T cells in a cohort of HIV-infected persons starting antiretroviral treatment (ART) in a high tuberculosis endemic area is described." (PMID 31419285, 2020). "In African patients, the optimal markers were lower nadir CD4 T-cell counts, greater weight and a history of tuberculosis whilst low current CD4 T-cell counts and >500 HIV RNA copies/mL were the clearest associations with HIV-SN in Indonesians." (PMID 31936167, 2020). "Significant differences in the two groups were observed in the number of medications administered, baseline CD4, initial diagnosis of tuberculosis and cryptococcal meningitis." (PMID 32758158, 2020). "These appeared to directly stem from participants’ self-awareness of immunodeficiency due to HIV.“I have low CD4 counts and I am also taking medicines for tuberculosis." (PMID 33097028, 2020). "In this way, CD4 is facilitating a shift away from symptom-based tuberculosis screening toward an approach of testing all those at high risk of disease." (PMID 30892272, 2019). "Multivariate logistic regression assessed the association between sexual risk taking behaviour controlling for gender, HIV clinical stage, HIV treatment status, Tuberculosis (TB) treatment status, and CD4 count." (PMID 31510974, 2019). "Proportions of CD4+ IFN-γ positive T cells largely reflected results from QFT/QFTin-vitro showing significantly higher responses for PHA in HCs as compared to tuberculosis patients for ICSBlood and ICSPBMCs." (PMID 31333654, 2019). "Most of the MLHIV who participated in the study and were not currently in treatment self-reported being ineligible for treatment based on criteria that were in effect at the time (a CD4 count <500 cells/mm3 or the presence of active tuberculosis disease)." (PMID 31644580, 2019). "This is poorly understood in tuberculosis (TB), an ancient, chronic disease, where CD4 T-cell immunity is of recognized importance." (PMID 30814998, 2019). "There should be strict monitoring of CD4+ T cell counts among individuals with tuberculosis coinfection." (PMID 31805857, 2019).
tuberculosis (continued). "It has been described that immunization with the tuberculosis subunit vaccine CAF01+H56 promotes lung homing of effector CD4+ T cells." (PMID 31130946, 2019). "Histoplasmosis and tuberculosis are frequently identified in patients with advanced HIV (CD4 T cells under 200/mm3)." (PMID 31404979, 2019). "In tuberculosis, the role of multifunctional CD4+ T cells has been well-elaborated, but the role of their CD8+ counterparts is less clear." (PMID 31681272, 2019). "There is less recovery of CD4+ T cells among human immunodeficiency virus patients infected with tuberculosis." (PMID 31805857, 2019). "The prevalence of microbiologically-confirmed tuberculosis was 62% and the median CD4 count was 86 cells per μL." (PMID 31155318, 2019). "In tuberculosis patients, Shannon entropy in CD4 was higher than CD8 or tissues, while tissue group showed the lowest Shannon entropy, although entropy of CD8 was not statistically higher than tissue group." (PMID 31173489, 2019). "Current guidelines recommend the use of the lateral flow urine lipoarabinomannan assay (LAM) in HIV-positive, ambulatory patients with signs and symptoms of tuberculosis (TB) only if they are seriously ill or have CD4 count ≤ 100 cells/μl." (PMID 31039161, 2019). "Retention was 89.0% in individuals who were underweight and 90.7% among patients screened positive for tuberculosis, and 90.4% among those with CD4 cell counts below 350 cells/mm3 at initiation of ART." (PMID 30953449, 2019). "Failure of CD4+ T cells reconstitution was higher among tuberculosis coinfected patients (48.8%) than mono-infected patients (13.7%)." (PMID 31805857, 2019). "For example, the IFNγ-release assay (IGRA) uses tuberculosis antigens to stimulate CD4+ T cells and measures the level of IFNγ release to determine previous tuberculosis exposure." (PMID 31581724, 2019). "Protection against tuberculosis challenge was correlated with levels of CD4 and CD8 T cells important for defense against tuberculosis." (PMID 31396406, 2019). "In Uganda, ART-naïve adults with CD4 counts ≤250 cells/μL are currently screened for tuberculosis and those with CD4 ≤100 cells/μL are also screened for cryptococcal antigen, similar to the case in South Africa." (PMID 30892272, 2019). "People with active tuberculosis have increased numbers of circulating regulatory CD4 T cells (that express CD25 + FoxP3+) and a greater IFN-γ response, compared to those with latent infection." (PMID 30760258, 2019). "The inability to provide a sputum sample is likely a reflection of the severity of illness in this cohort and will be less pronounced in outpatients with HIV and tuberculosis symptoms, who also typically have higher CD4 cell counts." (PMID 31155318, 2019). "tuberculosis immunity and that CD4+ T-lymphocytes were the primary mediators of this protection, shown both in transfer models and in gene-deficient mice." (PMID 30899256, 2019). "Prior guidelines limited eligibility to patients with CD4 counts ≤200 cells/μl and to pregnant or tuberculosis‐infected patients with counts ≤350 cells/μl." (PMID 29947442, 2018). "We also found anti-tuberculosis therapy [ATT] reduced PD1 expression on CD4+ T cells and restored IL-23R expression and IL-17 production." (PMID 29996789, 2018). "The most requested POC tests reported were serum creatinine (37%), CD4 count (37%), cholesterol (32%), tuberculosis (31%), and HIV viral load (23%)." (PMID 29843711, 2018). "Our findings suggest that tuberculosis pathogenesis results from a failure of CD4+Foxp3+ cell-mediated immune regulation." (PMID 30584243, 2018). "The different naive-like effector/memory CD4+ T cells reviewed here appear to have important and specific roles in protective immune responses in infectious diseases including tuberculosis." (PMID 30559746, 2018).
tuberculosis (continued). "Results demonstrated a survival benefit in patients newly diagnosed with tuberculosis and a CD4 count of less than 50/mm3 where antiretroviral therapy was commenced within 1–4 weeks of diagnosis." (PMID 29492737, 2018). "Less than 5% of the private facilities provided antiretroviral therapy (ART); had national ART guideline, baseline CD4 count or viral load and tuberculosis screening mechanisms." (PMID 29996821, 2018). "We aimed to determine if infection with Mycobacterium tuberculosis (M. tb), the etiological agent of tuberculosis, generates antigen-specific CD4+ TSCM and to characterize their functional ontology." (PMID 29545791, 2018). "Less than 5% of the private facilities provided ART using national guideline and had baseline CD4 count or viral load and tuberculosis screening mechanisms." (PMID 29996821, 2018). "Recent work has shown tuberculosis incidence after ART initiation is significantly lower in PLHIV with CD4 more than 500 cells/μl compared to their counterparts with lower CD4 counts [6▪]." (PMID 29698255, 2018). "Subgroup analyses for the primary outcome were prespecified based on baseline CD4 count, haemoglobin, clinical suspicion for tuberculosis; and by study site and calendar time." (PMID 30032978, 2018). "Antigen-specific CD4+ T cell responses to Mycobacterium tuberculosis (Mtb) infection are important for host defense against tuberculosis (TB)." (PMID 29983703, 2018). "Among the culture-positive tuberculosis participants, being unable to walk unaided, low BMI, low CD4 count, and being on ART remained strong prognostic indicators of poor outcomes." (PMID 29433509, 2018). "From this study, it was revealed that CD4 count, previous history of tuberculosis and smoking were the significant predictors of tuberculosis (p˂0.05) in HIV patients." (PMID 29997701, 2018). "We therefore studied phenotypic changes on MTB-specific CD4 T cells upon anti-tuberculosis treatment initiation in relation to the treatment response as determined by sputum culture." (PMID 30323818, 2018). "In multivariate analysis, the variables independently associated with increased IFN-γ production in response to PPD antigen were CD4+ T cell counts <200 cells/mm3 at baseline, age, site of tuberculosis, 800 mg efavirenz dose and follow-up CD4+ T cell counts." (PMID 28874142, 2017). "Several studies including this particular one have shown that tuberculosis treatment in HIV-TB patients reduces activation markers on CD4+ and CD8+ T cells in HIV patients co-infected with tuberculosis." (PMID 29937865, 2017). "In 2010, updated guidelines specified that pregnant women, patients with drug-resistant tuberculosis, and patients with nadir CD4 cell counts <100 cells/mm3 should be fast-tracked onto ART within 2 weeks of determining eligibility." (PMID 28095905, 2017). "Similar importance of parenteral priming vaccination has been demonstrated in a tuberculosis study, where priming turned out to be fundamental for eliciting CD4+ T cell response." (PMID 28467432, 2017). "Previous studies have demonstrated that RORγt is required in mucocutaneous immunity to Candida and systemic immunity to Mycobacterium, and decreased pSTAT3 expression reduced IL-17 production in CD4+ T cells from tuberculosis patients." (PMID 27926504, 2017). "Others have also demonstrated that measuring the levels of CD27 expression on M. tuberculosis–specific cytokine-producing CD4+ T cells has the potential to distinguish between tuberculosis and LTBI." (PMID 28329119, 2017). "We conducted a prospective study in Khayelitsha, South Africa, in hospitalized HIV-infected patients with CD4 cell counts <350/μL and microbiologically proved tuberculosis." (PMID 28363198, 2017). "Elsewhere, differences in IFNγ+TNFα+IL-2+, TNFα-single positive CD4+ T cells or a general increase in multi-cytokine producing T cells expression were observed between tuberculosis patients and contacts." (PMID 28241036, 2017).
tuberculosis (continued). "MHC-II molecules are continuously synthesized in response to infection, during which they are loaded with antigenic peptides in the MHC compartment and then exported to the plasma membrane, where they prime CD4+ T cells, mediating Th1 immunity to tuberculosis." (PMID 29204139, 2017). "Tuberculosis patients have fewer circulating CD4+CD161+Vα7.2+ cells producing both IFN-γ and IL-17 compared to latently infected individuals." (PMID 29075255, 2017). "Tuberculosis patients showed significantly decreased mIL-7R expression for both CD4+ (p = 0.01) and CD4- (p = 0.006) T cells." (PMID 28582466, 2017). "It documents their referral origin, their risk factors for infection, the CD4+ count, the WHO disease stage and the presence or history of tuberculosis." (PMID 28257647, 2017). "Male gender (p=0.001), CD4 cell count (p=0.045), tuberculosis (p=0.017), renal failure (p=0.013) and essential hypertension (p=0.026) met the criteria for inclusion in the multivariate analysis (p<0.2 from the univariate analysis)." (PMID 28533849, 2017). "Functional in vitro tests indicated diminished IL-7-induced STAT5 phosphorylation and impaired IL-7-promoted cytokine release of Mycobacterium tuberculosis-specific CD4+ T cells from tuberculosis patients." (PMID 28582466, 2017). "Another interesting finding was that Prevotella positively correlated with the peripheral CD4+ cells in new tuberculosis cases, and inversely correlated with recurrent tuberculosis cases." (PMID 29204120, 2017). "Both multiple cytokine producing CD4+ T cells as well as TNFα single positive T cells have been identified to discriminate between latent and active tuberculosis." (PMID 28241036, 2017). "Next, we measured IL-7-induced STAT5 phosphorylation and detected decreased phosphorylated STAT5 in CD4+ T cells from tuberculosis patients as compared to healthy contacts (p = 0.04)." (PMID 28582466, 2017). "The analysis of specific cytokine producing CD4+ T cells in active tuberculosis and latently infected tuberculosis patients revealed differences in expression of CD40L- T cells." (PMID 28241036, 2017). "For survival models, baseline CD4 count, gender, baseline age and either prevalent or incident tuberculosis." (PMID 28199360, 2017). "Previously, we identified SOCS3 as a marker of CD4+ T cells in tuberculosis, and others described SOCS3 as a central regulator of T-cell exhaustion and target of IL-7 in chronic viral infections." (PMID 28582466, 2017). "Hospitalized HIV-infected tuberculosis patients with CD4 counts <350 cells/μL were included; tuberculosis blood cultures were performed in all." (PMID 28369200, 2017). "Rifampin malabsorption is frequently observed in tuberculosis patients coinfected with human immunodeficiency virus (HIV) but cannot be predicted by patient factors such as CD4+ T cell count or HIV viral load." (PMID 29430306, 2017). "Changes in the immune system are closely related to the occurrence, development and outcome of tuberculosis, and T cells such as CD4+ and CD8+, which are related to cellular immunity, play important roles." (PMID 28225889, 2017). "Tuberculosis has been shown to improve the ability of HIV to replicate by activating CD4 T-lymphocyte cells and macrophages." (PMID 28959695, 2017). "We determined PD-1 mRNA expression of purified CD4+ T cells and found similar PD-1 expression among healthy contacts and tuberculosis patients prior to therapy." (PMID 28582466, 2017). "Among the first-line antituberculosis drugs, rifampin malabsorption is frequently observed among tuberculosis patients coinfected with HIV but cannot be predicted by factors such as CD4+ T cell count, viral load, or the presence of diarrhea." (PMID 29430306, 2017). "A case control study among Tuberculosis (TB) patients in Addis Ababa found that advanced HIV infection (WHO stage 3 & 4), baseline body mass index (BMI) <18.5 kg/m2 and baseline CD4 cell count were found to be associated with treatment failure in this study." (PMID 29095936, 2017).
tuberculosis (continued). "Whereas both CD4 and CD8 T cells are critical for anti-tuberculosis immunity, depletion of CD4 T cells is a major predisposing factor for lethal HIV-1 and tuberculosis coinfection." (PMID 29118429, 2017). "Immunity to tuberculosis (TB) is facilitated by two types of white blood cell; however, most research has focused on one: the CD4+ T cell." (PMID 28775896, 2017). "Elevated expression of T-bet and PD-1 in CD4+ T cells in the patients of tuberculosis was also reported." (PMID 27242794, 2016). "Pneumocystis pneumonia and tuberculosis were still the leading causes for the admission of HIV-infected patients in East China, and these patients tended to have very low CD4 cell counts." (PMID 27227959, 2016). "Only panels for HIV testing and tuberculosis smear microscopy are produced locally, whereas panels for clinical chemistry, haematology, bacteriology, CD4 counts and viral load are supplied by external agencies." (PMID 28879125, 2016). "HIV–mediated destruction of CD4+ T cells is important to tuberculosis pathology because these cells are necessary for the appropriate response to M. tuberculosis." (PMID 27462092, 2016). "CD4 counts were performed less frequently on younger children (p = 0.003), on children with tuberculosis (3.9% versus 11%, p<0.001), and on those with oral candidiasis (5.0% versus 11%, p = 0.008)." (PMID 27812166, 2016). "A randomized trial carried out in Haiti demonstrates that starting ART immediately in patients enrolled with less than 350 CD4/mm3 decreases the rates of death and incident tuberculosis compared to starting ART at 200 CD4/mm3." (PMID 27462361, 2016). "The evidence is now strong that initiating ART at high CD4 counts entails individual benefits worldwide, and that this is all the more true in low resource contexts where tuberculosis and other bacterial diseases are highly prevalent." (PMID 27462361, 2016). "Shiratusci in his study demonstrate the evaluation of the values of the lymphocyte subsets and there are noticed the decrease of values of CD3 and CD4 cells in patients with tuberculosis versus healthy subjects." (PMID 27275329, 2016). "Numerous studies have shown that the early recruitment of CD4+ T cells to the lung is the dominant factor determining bacterial control and lung pathology during tuberculosis." (PMID 27481246, 2016). "Patients who developed tuberculosis had the highest nadir CD4+ T lymphocyte (median of 107 cells/mm3, IQR: 48–218)." (PMID 27001753, 2016). "Other factors associated with early HAART initiation after an OI diagnosis were non-tuberculosis diagnosis and low CD4 counts at baseline." (PMID 27271083, 2016). "In that study, “feeling healthy” was the commonest reason given for ART refusal, despite a median CD4 count of 110 cells/μl and high rates of tuberculosis." (PMID 27504637, 2016). "It remains important to distinguish between pulmonary tuberculosis and sarcoidosis, because the CD4/CD8 ratio in the BALF of tuberculosis patient has also been reported to increase." (PMID 27930546, 2016). "Programed death ligand-1 signals via PD-1 on CD4+ T cells, and recently it was reported that Mycobacterium-induced PD-1 coordinates suppression of Th17 response in tuberculosis patients." (PMID 27867382, 2016). "Factors associated with starting HAART within 4 weeks of OI diagnosis were lower CD4 count at enrolment (p-<0.001), having a non-tuberculosis OI (p<0.001), study site (p<0.001), and more recent years of OI diagnosis (p<0.001)." (PMID 27271083, 2016). "In humans with M. tuberculosis infection, recent studies have found that memory like CD4+ T cells produce IL-22 and high level of IL-22 were present in bronchoalveolar lavage fluid of tuberculosis patients compared with those from healthy donors." (PMID 27031950, 2016). "In contrast, active tuberculosis patients exhibited increased numbers of Tim-3-expressing CD4+ and CD8+ T cells, which preferentially displayed polarized effector memory phenotypes." (PMID 27242794, 2016).